POSTN (periostin)
Diseases named in the same sentence as POSTN in open-access papers (continued):
Sharing a sentence is not in itself a finding about the gene and the disease.
glioma (continued). "In the test cohort, HOXA5, PTPN2, WT1, HOXD10, POSTN, ADAMDEC1 and MYBPH levels were elevated in glioma tissues with high-risk scores." (PMID 37812190, 2023). "We constructed a risk model using HOXA5, PTPN2, WT1, HOXD10, POSTN, ADAMDEC1 and MYBPH expression data from a cohort of patients in TCGA, and found that it had significant prognostic value for ATRX-wt glioma patients." (PMID 37812190, 2023). "Using RT–PCR and IHC analysis, It has been shown that Higher periostin expression is correlated with tumor grade, recurrence, progression, and shorter survival in human glioma patients and periostin overexpression promotes OSCC invasion and angiogenesis." (PMID 36224629, 2022). "A previous report showed that glioma stem cell-secreted POSTN can recruit M2-type TAM and the density of TAM correlates with POSTN expression level in glioblastoma multiformes (GBMs)." (PMID 36550569, 2022). "In their study, they showed that POSTN promoted glioma cell invasiveness in vitro, accompanied by MMP-9 expression." (PMID 35163164, 2022). "Glioma stem cells are recently shown to release periostin, which accumulates in the surrounding environment of blood vessels and acts as an inducer of TAM chemotaxis through signaling via the integrin receptor αvβ3." (PMID 34603399, 2021). "The extracellular matrix protein periostin is preferentially expressed on CD133+CD15+ glioma CSCs and recruits macrophages through integrin αvβ3 from the peripheral blood to the brain." (PMID 34235155, 2021). "Recent research studies have exhibited that glioma progression was modulated by circHIPK3 via interacting with miR-124-3p, circ_0079593 via sponging miR-182 and miR-433, and circ-POSTN via targeting miR-1205." (PMID 34017919, 2021). "Depletion of periostin in glioma CSCs leads to a reduction in the M2 population and alleviates tumor growth in glioblastoma xenografts." (PMID 34235155, 2021). "In murine gliomas, periostin was produced by glioma cancer stem cells (GSCs) residing in the perivascular niche and acted as a chemoattractant for brain macrophages through the integrin receptor αvβ3." (PMID 32019108, 2020). "Periostin is yet another glioma-derived protein, which interacts with integrins on microglia and macrophages in gliomas." (PMID 32019108, 2020). "Along with ABCC3, POSTN (periostin) was also identified to be the important regulator in the tumorigenesis and treatment of glioma." (PMID 32725165, 2020). "The vasculature within gliomas shows upregulated protein expression of the macromolecules periostin and tenascin C (TNC), which can prevent T cells from moving into glioma-associated vessels and prevent their migration into the brain parenchyma." (PMID 33193310, 2020). "The risk score was positively correlated to the oncogenes S100A4, TWIST1, CDH2, and POSTN, which were critically involved in glioma migration and invasion." (PMID 32733879, 2020). "Overexpression of TW:E12 forced dimerization constructs (FDCs) increased glioma cell invasion and upregulated pro-invasive proteins, including POSTN, in concert with cytoskeletal reorganization." (PMID 31540485, 2019). "Future studies will validate the scope of these mechanisms in additional glioma cell lines by analysis of direct POSTN promoter interactions, effects of kinase inhibition and establishing in vivo phenotypes in xenograft models." (PMID 31540485, 2019). "Since TW functional effects are regulated by phosphorylation and dimerization, we investigated how phosphorylation of serine 68 in TW regulates TW dimerization, POSTN expression, and invasion in glioma cells." (PMID 31540485, 2019). "POSTN in mouse cells is a direct transcriptional target of TW that phenocopies the pro-invasive function of TW in glioma cells." (PMID 31540485, 2019). "POSTN is highly expressed in glioma tissues and has been considered as a biomarker of glioma malignancy and recurrence." (PMID 31379707, 2019).
glioma (continued). "PTX3, FAPB7, POSTN, and PDPN are associated with increased glioma invasion, and both PDPN and CHI3L1 reportedly contribute to radio-resistance in glioblastoma." (PMID 29523123, 2018). "In this study, the glioma-related genes POSTN and CSFR1 were found to be uniquely under-expressed compared to the other three species." (PMID 29352201, 2018). "Our analysis of human GBM TCGA data provided evidence that POSTN is regulated by TW in human glioma, supporting the clinical relevance of findings in our xenograft studies." (PMID 29754406, 2018). "On the other hand, little is known about the role for periostin in glioma, aside from its expression being correlated with glioma tumor grade and survival." (PMID 29774119, 2018). "Further, a significant correlation between TW and POSTN expression levels was detected in a set of 38 human gliomas of various grades supporting potential regulatory interactions between the two genes." (PMID 29754406, 2018). "It has been reported that periostin expression is correlated with glioma grade and that secreted periostin promoted glioma invasion and adhesion." (PMID 29774119, 2018). "The mechanisms by which periostin contributes to glioma malignancy therefore requires more investigation." (PMID 29774119, 2018). "We found that hypoxia increased periostin (POSTN) expression in glioma cells and promoted the recruitment of macrophages." (PMID 27602954, 2016). "In this study, we demonstrated that hypoxia enhanced the recruitment of TAMs by upregulating POSTN expression in glioma cells." (PMID 27602954, 2016). "Collectively, these data demonstrate that hypoxia-inducible POSTN expression enhanced the chemotactic effect of glioma cells on macrophages." (PMID 27602954, 2016). "Deletion of periostin in glioma stem cells resulted in decreased M2 TAM density, reduced tumor growth, and consequently increased survival in glioblastoma xenografts." (PMID 26980947, 2016). "We observed that POSTN+ cells were located closer to perivascular niches in low HIF-1α glioma specimens." (PMID 27602954, 2016). "The enhanced directional migration of macrophages toward hypoxic areas has been attributed to the hypoxia-inducible expression of POSTN in glioma cells." (PMID 27602954, 2016). "Our results confirm that both HIF-1α and POSTN expression increased as the grade of the glioma increased." (PMID 27602954, 2016). "While SDF-1α and OPN were also slightly increased in perivascular areas in high-HIF-1α glioma tissue, their expression levels and areas were much smaller than those of POSTN." (PMID 27602954, 2016). "In glioma, Let-7f inhibited the cell proliferation, migration, and invasion by repressing the expression of periostin." (PMID 27034956, 2016). "To explore the relationships between hypoxia, POSTN expression and the infiltration of TAMs in gliomas, we performed immunohistochemical (IHC) staining on sections obtained from different grade gliomas." (PMID 27602954, 2016). "To explore the connection between POSTN expression, GSLCs and hypoxia in gliomas, we examined the POSTN expression pattern in human GBM surgical specimens that exhibited different levels of HIF-1α." (PMID 27602954, 2016). "Collectively, our findings demonstrate that in glioma cells, hypoxia-induced increases in POSTN expression are mediated via the TGF-α/RTK/PI3-K pathway." (PMID 27602954, 2016). "Among the significant correlation changes in the network, we find three genes (MYT1L, EGFR, POSTN) known to have meaningful roles in glioma pathogenesis." (PMID 21756334, 2011). "Interestingly, among the transcripts down-regulated in DUSP8-GFP GdEC#1 and up-regulated in sh-DUSP8-GFP GdEC#1 we found periostin (POSTN) a matricellular protein that has been associated with glioma progression, particularly with glioma angiogenesis." (PMID 41029387, 2025). "GSCs preferentially secrete POSTN proteins over non‐stem cell glioma cells." (PMID 40583858, 2025).
glioma (continued). "Interestingly, we found that most of these ligands (e.g., CSF1, CXCL8, POSTN) 21, 32, 43 are broadly expressed in different glioma subclusters, whereas SPP1 is specifically expressed in the CEBPB+ GBM subcluster." (PMID 38994023, 2024). "To determine the molecular mechanism by which POSTN regulates CD70 expression in glioma, we performed chromatin immunoprecipitation enrichment analysis (ChEA) of RNA-seq data from HMC3 cells to identify transcription factors that potentially mediate transcriptional changes in microglia." (PMID 39227950, 2024). "To further assess the expression of FOSL1 in glioma and the association between FOSL1 expression and prognosis in glioma patients, we examined the expression of POSTN in normal brain and glioma tissues and analyzed data from the TCGA, CGGA and Rembrandt databases." (PMID 39227950, 2024). "Similarly, an inverse correlation is reported between periostin expression and overall survival in glioma." (PMID 38969910, 2024). "POSTN expression is crucial for the angiogenesis of gliomas." (PMID 37063864, 2023). "In glioma, POSTN may regulate resistance to anti-VEGF-A therapy by upregulating the expression of TGFβ1 and HIF1α." (PMID 37180146, 2023). "Besides, in glioblastoma, glioma stem cells secrete periostin, which recruits the tumor-promoting M2 subtype of macrophages into glioblastoma tissues, causing the malignant biological behavior of glioblastoma." (PMID 37771444, 2023). "Periostin generated by GSCs, accruing in the perivascular niche, induces integrin αvβ3 receptor signaling to recruit TAMs (M2-like), maintain the microglia or macrophages M2 phenotype and promote extravasation and migration in the glioma environment." (PMID 37759870, 2023). "In glioblastoma, for instance, there is a negative association between periostin expression and miR-599, and overexpression of miR-599 inhibits glioma cell motility and invasion by down-regulating periostin expression." (PMID 36224629, 2022). "Likewise, the PERIOSTIN signaling pathway has been reported to play an important role in glioma invasion and resistance to angiogenesis." (PMID 35855654, 2022). "Periostin is a matrix protein that recruits pro-tumoral macrophages and enhances GB progression in mice, and recently, it has been reported to be expressed by PC in gliomas, favoring angiogenesis." (PMID 35419364, 2022). "Moreover, hypoxia increases POSTN expression in glioma cells and promotes the recruitment of macrophages." (PMID 36275720, 2022). "With respect to glioblastoma, researchers found that periostin (POSTN) from glioma stem cells (GSCs) recruits monocyte-derived macrophages from the peripheral blood through integrin αvβ3 to induce an M2 phenotype, and POSTN knockdown in GSCs inhibits tumor growth." (PMID 33391518, 2021). "We previously reported that TW and POSTN promote glioma cell invasion." (PMID 31540485, 2019). "On the other hand, little is known about the role of periostin in glioma cell migration." (PMID 29774119, 2018). "Importantly, we also validated the clinical relevance of POSTN as a putative TW target gene in human glioma and GBM gene expression databases." (PMID 29754406, 2018). "We previously showed that POSTN is important for glioma tumorigenicity." (PMID 29754406, 2018). "The high rate of POSTN expression in GSLCs in low HIF-1α glioma specimens may explain this POSTN distribution pattern." (PMID 27602954, 2016). "A recent study showed that in gliomas, POSTN is mainly secreted by GSLCs." (PMID 27602954, 2016). "However, pre-incubating hypoxia-stimulated U87 or U251 glioma cells in culture media containing an anti-POSTN antibody attenuated this macrophage migration-promoting effect." (PMID 27602954, 2016). "To determine whether the hypoxia-inducible expression of POSTN in glioma cells is capable of attracting macrophages, we performed a series of migration and invasion assays." (PMID 27602954, 2016).
glioma (continued). "As HIF-1α positive regions expanded, more non-glioma stem-like cells began to express POSTN." (PMID 27602954, 2016). "Moreover, this hypoxia-inducible effect was impaired when POSTN expression was silenced in U87/U251 cells or when a HIF inhibitor (ACF) was added to the culture medium of the glioma cells during hypoxia stimulation." (PMID 27602954, 2016). "Because hypoxia and POSTN are associated with the enrichment of TAMs in gliomas, we next sought to determine whether the hypoxia-induced upregulation of POSTN expression attracted more TAMs and subsequently promoted glioma progression." (PMID 27602954, 2016). "Furthermore, glioma stem cells recruited monocyte-derived macrophages by secreting CSCs-derived periostin, thereby supporting tumor growth 50; additionally, the loss of PTEN and NF1 in glioma stem cells upregulated LOX and chemokines, respectively, to attract TAMs 51,52." (PMID 39479456, 2024). "On the other hand, we found that POSTN is an important mediator of the effects of endothelial cell-derived EVs on tumorigenic properties of GSCs promoting processes such as proliferation, self-renewal and migration, all of them essential hallmarks for glioma progression." (PMID 38347567, 2024). "In addition, survival analysis of datasets from The Cancer Genome Atlas (TCGA), the Chinese Glioma Genome Atlas (CGGA) and Rembrandt collection revealed that high POSTN expression was associated with a worse prognosis than low POSTN expression in glioma patients (p < 0.0001)." (PMID 39227950, 2024). "The expression levels of POSTN, CHI3L1, SAA1, and MMP9 were assessed in various glioma cell lines (U87, U251, U118, A172, T98G, SF295, LN229, and SF126) using qRT-PCR." (PMID 39574472, 2024). "PTX3 promotes the transcription and secretion of periostin (POSTN), which triggers activation of the MAP-ERK, which promotes EMT-like processes in glioma cells." (PMID 39201656, 2024). "Taken together, our evidence indicates that the predictive model constructed using POSTN, CHI3L1, SAA1 and MMP9 expression had significant prognostic value for patients with glioma." (PMID 39574472, 2024). "To verify the tumor-promoting effect of POSTN in GBM, we knocked down POSTN in the murine glioma cell line GL261 and orthotopically injected normal and POSTN-knockdown GL261 cells into C57BL/6J mice." (PMID 39227950, 2024). "To ensure accuracy, we compared the gene expressions of POSTN, CHI3L1, SAA1, and MMP9 in these glioma cells using the CCLE database and confirmed that the classification was consistent." (PMID 39574472, 2024). "Previous studies have extensively documented the dysregulation and oncogenic properties of POSTN, CHI3L1, SAA1, and MMP9 in various cancer types, including gliomas." (PMID 39574472, 2024). "The genes POSTN, CHI3L1, SAA1, and MMP9 were screened to establish a predictive model, which exhibited a significant correlation with glioma prognosis and served as independent prognostic factors." (PMID 39574472, 2024). "We identified five critical genes (HOXA2, CHI3L1, POSTN, OASL, and ZNF474) with substantial roles in the glioma context." (PMID 38473752, 2024). "Glioma cell proliferation, including glioma stem cells, results in the secretion of cytokines and chemokines such as MIC-1, periostin, IL-33, and MCP-1, which recruit blood-borne monocytes and macrophages to the tumor site, polarizing them into M2 TAMs." (PMID 37234776, 2023). "Periostin (POSTN) was found to be directly related to glioma tumor grade and recurrence, promoting glioma cell invasion and adhesion while increasing the survival rate of glioma stem cells." (PMID 37700319, 2023). "Consequently, miR-599 could be utilized to suppress periostin expression in human gliomas." (PMID 36224629, 2022).
glioma (continued). "Additionally, POSTN, an extracellular matrix component produced by glioma stem cells, provides an efficient binding site for αVβ3 integrins on the cell surface of peripheral monocytes and M2-GAMs to promote the extravasation and migration in the glioma microenvironment." (PMID 36275720, 2022). "Genes common to the top 5 activated pathways include POSTN, MMP9, CEBPB, CEBPD, and IGFBP5, which reportedly participate in glioma growth, invasion, and immunosuppression." (PMID 35814469, 2022). "Periostin expression correlates with TAM density, and depletion of periostin in glioblastoma cells reduces TAM recruitment and inhibits tumor growth in mice bearing glioma stem-like cell-derived xenografts via integrin αvβ3 signaling." (PMID 34503065, 2021). "In patients with glioma, IHC analysis revealed the positive correlation between HIF-1α expression, periostin (POSTN) expression, and the infiltration of TAMs (CD11b+) and M2 type TAMs (CD206+) in tumor sections." (PMID 32486098, 2020). "Periostin protein expression was evaluated by both western blot and in a tissue microarray (TMA) composed by 138 glioma tumor samples of different histological grades." (PMID 31052505, 2019). "To investigate the connection between hypoxia and POSTN production, we performed immunofluorescence staining for POSTN and HIF-1α in sections from different grade gliomas." (PMID 27602954, 2016). "POSTN, TGF-β, and M-CSFR were expressed at higher levels in gliomas and HMDM cells that were exposed to hypoxia than in cells that were cultured under normoxic conditions." (PMID 27602954, 2016). "Both POSTN expression and TAM infiltration were concentrated in perivascular areas in low HIF-1α glioma tissues, but their distribution became more disseminated as the expression of HIF-1α increased." (PMID 27602954, 2016). "We found that the expression level and range of POSTN were each much higher and more disseminated in high-HIF-1α-expressing glioma sections than in low-HIF-1α expressing glioma specimens." (PMID 27602954, 2016). "A correlation between the distribution of POSTN and CD206+ TAMs was also found in gliomas with different grades." (PMID 27602954, 2016). "We found that HIF-1α expression, POSTN expression, and the infiltration of TAMs (CD11b+) and M2 type TAMs (CD206+) increased as the grade of the glioma increased." (PMID 27602954, 2016). "The development of anti-periostin neutralizing antibodies has produced good results in mouse model of breast and ovarian cancer but no data are available for glioma therapy." (PMID 38969910, 2024). "A receiver operating characteristic curve analysis indicated that HOXA5, PTPN2, WT1, HOXD10, POSTN, ADAMDEC1 and MYBPH had significant prognostic value for the survival of ATRX-wt glioma patients (AUC = 0.84, 0.81, 0.79, 0.91, 0.80, 0.79 and 0.85, respectively)." (PMID 37812190, 2023). "In conclusion, our study revealed that an immune signature based on HOXA5, PTPN2, WT1, HOXD10, POSTN, ADAMDEC1 and MYBPH expression effectively predicted the prognosis of ATRX-wt glioma patients, and demonstrated that immunotherapy was effective for low-risk patients." (PMID 37812190, 2023). "In another study, periostin gene silencing, using small interfering RNA, decreased TGF-β-induced expression of fibronectin and vimentin, partly through reduced Smad2, AKT and FAK phosphorylation, as well as invasion and migration of U-87 MG glioma cells." (PMID 32019108, 2020). "Of clinical and functional relevance, TW and POSTN expression are highly correlated and predictive of survival in GBM patient samples and both promote highly overlapping pro-invasive and tumorigenic phenotypes in glioma cells." (PMID 31540485, 2019). "High levels of CHI3L1 and EMP3 as well as FAPB7 and POSTN were reported as negative prognostic biomarkers in glioma." (PMID 29523123, 2018).